ADIPOQ (adiponectin, C1Q and collagen domain containing)
Description:
Important adipokine involved in the control of fat metabolism and insulin sensitivity, with direct anti-diabetic, anti-atherogenic and anti-inflammatory activities. Stimulates AMPK phosphorylation and activation in the liver and the skeletal muscle, enhancing glucose utilization and fatty-acid combustion. Antagonizes TNF by negatively regulating its expression in various tissues such as liver and macrophages, and also by counteracting its effects. Inhibits endothelial NF-kappa-B signaling through a cAMP-dependent pathway. May play a role in cell growth, angiogenesis and tissue remodeling by binding and sequestering various growth factors with distinct binding affinities, depending on the type of complex, LMW, MMW or HMW.
Synonyms: ACRP30; apM-1; ACDC; APM1; GBP28; adiponectin; ADIPQTL1; ADPN
Tractability: Antibody: UniProt places it where antibodies can reach, with high confidence; its Gene Ontology location is reachable by antibodies, with high confidence; UniProt predicts a signal peptide or a membrane-spanning region.
Gene: Protein-coding gene on chromosome 3 (186,842,704 to 186,858,463, forward strand). Ensembl gene ENSG00000181092.
Subcellular location: Secreted
Pathways (Reactome):
Developmental Biology: Transcriptional regulation of white adipocyte differentiation
Gene expression (Transcription): MLL4 and MLL3 complexes regulate expression of PPARG target genes in adipogenesis and hepatic steatosis
Metabolism: AMPK inhibits chREBP transcriptional activation activity
Gene Ontology:
Molecular function: hormone activity; protein binding; protein homodimerization activity; sialic acid binding; cytokine activity; extracellular matrix structural constituent; signaling receptor binding; identical protein binding; protein serine/threonine kinase activator activity
Biological process: adiponectin-activated signaling pathway; low-density lipoprotein particle clearance; negative regulation of blood pressure; negative regulation of canonical NF-kappaB signal transduction; negative regulation of cholesterol import; negative regulation of ERK1 and ERK2 cascade; negative regulation of fat cell differentiation; negative regulation of granulocyte differentiation; negative regulation of heterotypic cell-cell adhesion; negative regulation of macrophage derived foam cell differentiation; negative regulation of macrophage differentiation; negative regulation of phagocytosis; negative regulation of platelet-derived growth factor receptor signaling pathway; negative regulation of receptor-mediated endocytosis; negative regulation of synaptic transmission; negative regulation of tumor necrosis factor production; negative regulation of tumor necrosis factor-mediated signaling pathway; negative regulation of vascular associated smooth muscle cell migration; negative regulation of vascular associated smooth muscle cell proliferation; positive regulation of cAMP/PKA signal transduction; positive regulation of cholesterol efflux; positive regulation of interleukin-8 production; positive regulation of monocyte chemotactic protein-1 production; positive regulation of myeloid cell apoptotic process; positive regulation of renal albumin absorption; and 26 more
Cellular component: cell surface; extracellular matrix; extracellular region; endoplasmic reticulum; non-collagenous component of interstitial matrix
Genetic constraint (gnomAD): Loss-of-function variants: 22 observed, 18.85 expected, observed/expected ratio (o/e) 1.17, 90% interval 0.83 to 1.65. The upper end of that interval is the gene's LOEUF score, 1.65, which puts it in group 6 of 6, group 1 being the genes least tolerant of losing a copy. Missense variants: 323 observed, 324.15 expected, observed/expected ratio (o/e) 1, 90% interval 0.91 to 1.09. Synonymous variants: 124 observed, 132.48 expected, observed/expected ratio (o/e) 0.94, 90% interval 0.81 to 1.09.
Homologues: Orthologues: chimpanzee ADIPOQ (99% identical), macaque ADIPOQ (96% identical), rabbit ADIPOQ (86% identical), dog ADIPOQ (85% identical), mouse Adipoq (83% identical), pig ADIPOQ (83% identical), guinea pig ADIPOQ (81% identical), rat Adipoq (69% identical), zebrafish adipoqb (58% identical), tropical clawed frog adipoq (57% identical), zebrafish adipoqa (48% identical). Paralogues in human: C1QTNF9 (47% identical), C1QTNF9B (46% identical), C1QTNF7 (41% identical), C1QTNF2 (40% identical), COL10A1 (39% identical), OTOL1 (39% identical), COL8A2 (37% identical), C1QTNF5 (36% identical), COL8A1 (36% identical), C1QC (36% identical), C1QB (33% identical), C1QL2 (30% identical), and 11 more.
Diseases named in the same sentence as ADIPOQ in open-access papers:
ADIPOQ is named in the same sentence as 169 diseases in open-access papers, as found by Europe PMC text mining. Sharing a sentence is not in itself a finding about the gene and the disease. The quoted sentences say what the papers report.
Obesity (159 papers, 2007 to 2026). Accumulation of substantial excess body fat. "Studies established a direct link between the polymorphisms in leptin (LEP) and adiponectin (ADIPOQ) genes, with excessive weight gain and obesity." (PMID 40186666, 2025). "In the South Indian population, polymorphisms in the ADIPOQ gene (e.g., rs2241766 and rs1501299) influenced serum adiponectin levels and conferred differential risks for obesity and T2DM." (PMID 40004938, 2025). "Genetic variation in the ADIPOQ gene has been extensively studied due to its influence on circulating adiponectin levels and associated obesity risk." (PMID 40565591, 2025). "Genetically, we identified two variants, rs1501299 and rs3774261, as key ADIPOQ variants associated with obesity in patients with PCOS." (PMID 41598180, 2025). "To understand the genetic architecture of ADIPOQ variants and their association with obesity in PCOS, we conducted linkage disequilibrium (LD) mapping and single-variant association studies." (PMID 41598180, 2025). "Our study provides evidence that the ADIPOQ variants rs1501299 and rs3774261 are significantly associated with obesity in women with PCOS." (PMID 41598180, 2025). "Polymorphism of the gene encoding adiponectin (ADIPOQ) is shown to be associated with low circulating levels of adiponectin, IR, and obesity." (PMID 40385742, 2025). "An upregulation of TLR4 (P < 0.05), CD68 (P < 0.05), SPP1 (P < 0.05) and CCL2 (P < 0.05) together with a downregulation (P < 0.05) of ADIPOQ levels in the jejunum from patients with obesity-associated T2D were found." (PMID 38315242, 2024). "Some of these genetic variations also elevate the risk of developing T2DM, such as TM6SF2, TCFL2, and SREBF2, while others are associated with obesity risk, like ADIPOQ and SH2B1." (PMID 38248762, 2024). "In humans, downregulation of serum AdipoQ can be associated with clinical cases of obesity, type 2 diabetes, cardiovascular disease, Alzheimer’s disease and different types of cancer (e.g., breast cancer)." (PMID 38027109, 2023). "In recent years, Choubey and coworkers have extensively studied the role of ADIPOQ on mice testicular activity; in particular, that of the ADIPOQ/ADIPORs system in the prevention of aging and obesity-associated testicular reproductive dysfunctions." (PMID 36830390, 2023). "Previously, hypermethylation of the human adiponectin gene (ADIPOQ) was reported to be associated with obesity." (PMID 36836658, 2023). "Given the significance of gene-gene interactions, more studies are required to determine the substantial contributions of ADIPOQ gene variants to the emergence of obesity and other characteristics of metabolic diseases to clarify the pathological processes." (PMID 37151957, 2023). "Three exons make up the ADIPOQ obesity-associated variants, and the rs2241766, rs266729, and rs1501299 were frequently studied." (PMID 37151957, 2023). "Several common variants of the ADIPOQ gene are reported in the literature to be associated with obesity, T2DM, and metabolic syndrome, but these results are ethnospecific." (PMID 37888112, 2023). "Single nucleotide polymorphisms (SNPs) such as rs1501299 (276G>T), rs266729 (_11377C>G) and rs822396 are among the most common polymorphisms of ADIPOQ and have been evaluated for their association with obesity." (PMID 36551995, 2022). "In general, different results in the relationship of genetic variants of ADIPOQ with obesity and metabolic syndrome can be due to differences in ethnic populations, communication methods, and the study power." (PMID 35436947, 2022). "The BMI increasing alleles of FTO, LEPR and ADIPOQ genetic variants are common in Pakistani individuals thus increasing their risk towards obesity." (PMID 36126070, 2022). "This study aimed to determine the association of four variants of the ADIPOQ gene with serum adiponectin, cortisol levels and obesity status." (PMID 35436947, 2022).
Obesity (continued). "Several other investigations have confirmed the association between obesity and the methylation status of LEP and ADIPOQ, which has been proposed to promote obesity-associated insulin resistance and metabolic derangements." (PMID 35163268, 2022). "The rs2241766 SNP of ADIPOQ is thought to be a candidate marker for obesity due to its significant association with BMI-defined obesity in various populations." (PMID 36126070, 2022). "It was also displayed that the +276 G/T (rs1501299) polymorphism of the ADIPOQ gene is associated with the risk of obesity in Caucasians." (PMID 35366291, 2022). "The population of Indonesia has a high genetic diversity; thus, investigation of the association of SNPs in ENPP1 and ADIPOQ genes with obesity, and its related traits, is of potential interest." (PMID 34208364, 2021). "ADIPOQ has been proposed to be a mediator of obesity-associated metabolism and to have direct effects on the development and progression of various types of malignancies." (PMID 34329197, 2021). "There are several lines of evidence that miRNAs are implicated in the obesity-related downregulation of ADIPOQ expression." (PMID 34943849, 2021). "The plasma concentration of ADIPOQ decreases in conditions of obesity and increases with weight loss." (PMID 34438765, 2021). "Most of the variants in this category were located in ADIPOQ, the second most common gene according to the number of obesity-associated variants among Arabs." (PMID 34131278, 2021). "The aim of this research was to study the polymorphisms of two obesity-associated genes ADIPOQ and FTO that are also related to the pathogenesis of BC." (PMID 34345232, 2021). "Adiponectin, encoded by the ADIPOQ gene, is of particular interest in metabolic syndrome because of its inverse relation with insulin sensitivity and obesity." (PMID 33232281, 2020). "Then, we investigated (by genotyping) the entire ADIPOQ gene in people with severe obesity, to determine the potential presence of genetic variants (SNPs) and/or mutations, and their correlation to biochemical variations." (PMID 31547312, 2019). "A short-term intervention with CAD induced a higher relative abundance of L. Lactis, B. pseudolongum, and higher mRNA levels of genes AdipoQ and Irs1 involved in obesity associated pathways compared with CHPD." (PMID 31708891, 2019). "Adiponectin (ADIPOQ), an adipocytokine that regulates energy and material metabolism, is implicated in the development of multiple metabolic disorders including obesity and type II diabetes." (PMID 30885128, 2019). "Then, in our cohort of people with severe obesity, we analyzed the possible influence of the genetic background in the ADIPOQ gene on the weight loss, as well as on the amelioration of the biochemical profile." (PMID 31547312, 2019). "In the view of gene-gene interactions, further research is necessary to ascertain the significant implication of ADIPOQ gene variants towards the development of obesity and other features of metabolic disorders to elucidate the pathological processes." (PMID 30265726, 2018). "Association between ADIPOQ polymorphisms haplotypes, obesity and metabolic syndrome risk in study population." (PMID 30265726, 2018). "Here, we aimed to investigate the association of two intronic variants in ADIPOQ gene, -3971A>G (rs822396) and +276G>T (rs1501299) with obesity and metabolic syndrome." (PMID 30265726, 2018). "Many studies have reported that single-nucleotide polymorphisms (SNPs) of the adiponectin (ADIPOQ) gene have been associated with obesity and its related disorders." (PMID 30265726, 2018). "Epidemiological study also suggested that low level of plasma ADIPOQ was associated with higher risk of atherosclerosis, diabetes, insulin resistance, obesity, and cancers." (PMID 29156813, 2017).
Obesity (continued). "The substitution (rs17366743 C/T) in human ADIPOQ exon 3, which is proximal to ovine c.515G/A, has been reported to be associated with obesity and variation in adiponectin levels in some populations." (PMID 28604630, 2017). "In summary, only FTOrs9939609 was associated with obesity related-traits, while PPARG2rs1801282 and ADIPOQ rs4632532 were involved in lipidmetabolism." (PMID 27560839, 2016). "LEP has been directly associated with obesity, while ADIPOQ has been inversely associated with obesity and visceral fat accumulation." (PMID 27857161, 2016). "Association studies of ADIPOQ polymorphisms, adiponectin levels and obesity phenotypes using samples of African American population from the Jackson Heart Study (JHS) cohort." (PMID 27703473, 2016). "In the current study, we report that LEP and ADIPOQ DNA methylation levels, measured in paired adipose tissues and blood samples, are associated with obesity-related anthropometric variables and fasting LDL-C levels." (PMID 25929254, 2015). "In the present study, we examined the relationship between ADIPOQ polymorphisms and adiponectin levels and obesity phenotypes in African American participants from the JHS." (PMID 26290432, 2015). "Obesity has been associated with higher plasma concentration of leptin and lower plasma concentration of ADIPOQ in horses." (PMID 25938677, 2015). "The ADIPOQ gene has been found to be strongly associated with obesity and serum adiponectin levels among numerous study populations." (PMID 26290432, 2015). "In order to explore the influence of PEA on the association between ADIPOQ SNPs and obesity we stratified the analysis by PEA levels expressed in two categories (low vs. high PEA) based on the median value of this variable (15 %)." (PMID 26290432, 2015). "This study provides further evidence that LEP DNA methylation levels in blood cells and ADIPOQ DNA methylation levels in SAT are associated with obesity-related anthropometric measures." (PMID 25929254, 2015). "The ADIPOQ gene is located on chromosome 3q27, which has been demonstrated to be a susceptibility locus for obesity by several genome-wide scan studies." (PMID 24740426, 2014). "Adiponectin (ADIPOQ), an insulin sensitizer secreted principally by adipocytes, is inversely associated with body fat, obesity, insulin resistance through the stimulation of insulin secretion, increment of fatty acid combustion and energy consumption." (PMID 25516230, 2014). "Better designed studies that consider confounding factors in larger sample sizes with a focus on the relationship between ADIPOQ-rs2241766G/T polymorphisms and obesity are required to confirm our findings." (PMID 24740426, 2014). "Better-designed studies that consider confounding factors and assess larger sample sizes with a focus on ADIPOQ-rs2241766G/T polymorphisms and obesity are required in the future." (PMID 24740426, 2014). "FABP4 takes part in the predisposition of cardiac fats in obese persons, and ADIPOQ upregulation is the main cause of type 2 diabetes and obesity." (PMID 23922792, 2013). "Some of the obesity-associated genes in this study have known functions, ADIPOQ is known to decrease body weight by increasing lipid oxidation in muscles and other organs, and UCP3 plays an important role in human energy homeostasis." (PMID 23950976, 2013). "After adjusting for age, sex and admixture, significant associations with obesity were found for 6 genes in the case-control study (ADIPOQ, FTO, TMEM18, INSIG2, FAIM2/BCDIN3 and BDNF)." (PMID 23950976, 2013). "The TNF-α, IL-6 and AdipoQ polymorphisms were selected considering the participation of these cytokines in underlying mechanisms of obesity-related metabolic disturbances, such as inflammation and insulin resistance." (PMID 23176569, 2012). "In the present study, three SNPs located on the ADIPOQ gene, which have previously been studied for an association with obesity in other ethnic groups, were evaluated in healthy Koreans." (PMID 21603224, 2011).